CDKN2AIP (CDKN2A interacting protein)
Description:
Regulates DNA damage response in a dose-dependent manner through a number of signaling pathways involved in cell proliferation, apoptosis and senescence.
Synonyms: CARF; XTBD2; FLJ20036
Tractability: PROTAC: UniProt records ubiquitination sites on it; ubiquitination databases record sites on it; its protein half-life has been measured.
Gene: Protein-coding gene on chromosome 4 (183,444,635 to 183,449,064, forward strand). Ensembl gene ENSG00000168564.
Subcellular location: Nucleus, nucleoplasm
Subcellular location (Human Protein Atlas): Nucleoplasm
Gene Ontology:
Molecular function: protein binding
Biological process: DNA damage response; negative regulation of cell growth; positive regulation of cell growth; positive regulation of signal transduction; regulation of protein stability
Cellular component: granular component; nucleolus; nucleoplasm; nucleus
Genetic constraint (gnomAD): Loss-of-function variants: 10 observed, 34.61 expected, observed/expected ratio (o/e) 0.29, 90% interval 0.18 to 0.49. The upper end of that interval is the gene's LOEUF score, 0.49, which puts it in group 2 of 6, group 1 being the genes least tolerant of losing a copy. Missense variants: 631 observed, 619.78 expected, observed/expected ratio (o/e) 1.02, 90% interval 0.95 to 1.09. Synonymous variants: 256 observed, 247.4 expected, observed/expected ratio (o/e) 1.03, 90% interval 0.93 to 1.15.
Homologues: Orthologues: chimpanzee CDKN2AIP (100% identical), macaque CDKN2AIP (98% identical), pig CDKN2AIP (93% identical), dog CDKN2AIP (92% identical), rabbit CDKN2AIP (90% identical), guinea pig CDKN2AIP (88% identical), rat Cdkn2aip (87% identical), mouse Cdkn2aip (84% identical), tropical clawed frog cdkn2aip (38% identical), zebrafish cdkn2aip (26% identical), Caenorhabditis elegans paxt-1 (14% identical), Drosophila melanogaster CG31301 (11% identical). Paralogues in human: NKRF (15% identical), XTBD1 (8% identical).
Diseases named in the same sentence as CDKN2AIP in open-access papers:
CDKN2AIP is named in the same sentence as 15 diseases in open-access papers, as found by Europe PMC text mining. Sharing a sentence is not in itself a finding about the gene and the disease. The quoted sentences say what the papers report.
osteosarcoma (3 papers, 2021 to 2024). A usually aggressive malignant bone-forming mesenchymal neoplasm, predominantly affecting adolescents and young adults. "In osteosarcoma, circFOXP1 expression was also increased and promoted angiogenesis by directly binding to microRNA-127-5p and regulating CDKN2AIP expression." (PMID 38745044, 2024). "circFOXP1 can promote angiogenesis by regulating the miR-127-5p/CDKN2AIP signaling pathway in osteosarcoma." (PMID 36072625, 2022). "In conclusion, circFOXP1 promoted angiogenesis by regulating miR-127-5p/CDKN2AIP signaling pathway in osteosarcoma." (PMID 34637672, 2021). "In our study, we found that CDKN2AIP was obviously upregulated in osteosarcoma and was positively correlated to angiogenesis." (PMID 34637672, 2021). "In this work, we found that circFOXP1 is overexpressed in osteosarcoma and promotes the growth and angiogenesis of osteosarcoma via regulating miR-127-5p/CDKN2AIP axis." (PMID 34637672, 2021). "We found that circFOXP1 promotes angiogenesis by regulating miR-127-5p/CDKN2AIP signaling pathway in osteosarcoma." (PMID 34637672, 2021). "We found that circFOXP1 expression was increased in osteosarcoma, and could promote angiogenesis in osteosarcoma through upregulating CDKN2AIP expression." (PMID 34637672, 2021). "Here, we hypothesize that circRNAs play a role in osteosarcoma angiogenesis and aim to investigate the relationship between circRNAs and CDKN2AIP, and their effects on angiogenesis in osteosarcoma." (PMID 34637672, 2021). "To study the mechanism underlying circFOXP1 promoting the angiogenesis of osteosarcoma, we further explored the regulatory effect of circFOXP1 on CDKN2AIP, and found that both CDKN2AIP mRNA and protein expression decreased after inhibiting circFOXP1 expression in osteosarcoma." (PMID 34637672, 2021). "Thus, circFOXP1/miR-127-5p/CDKN2AIP regulation axis plays an essential role in osteosarcoma angiogenesis." (PMID 34637672, 2021). "CDKN2AIP expression was obviously reduced after the treatment of miR-127-5p mimic in osteosarcoma." (PMID 34637672, 2021). "In our study, we identified that circFOXP1 could promote angiogenesis by regulating miR-127-5p/CDKN2AIP signaling pathway in osteosarcoma." (PMID 34637672, 2021). "Therefore, circFOXP1 could promote angiogenesis by regulating miR-127-5p/CDKN2AIP signaling pathway in osteosarcoma." (PMID 34637672, 2021). "Therefore, our findings highlighted that circFOXP1 could promote angiogenesis by regulating miR-127-5p/CDKN2AIP signaling pathway in osteosarcoma." (PMID 34637672, 2021).
Crohn disease (1 paper, 2021). A gastrointestinal disorder characterized by chronic inflammation involving all layers of the intestinal wall, noncaseating granulomas affecting the intestinal wall and regional lymph nodes, and transmural fibrosis. "CDKN2AIP is critical for the DNA damage response and TBC1D1 has been linked to Crohn’s disease, and lymphocyte count." (PMID 33563976, 2021).
diabetes (1 paper, 2025).
Infertility (1 paper, 2022). "Our data showed that reduced expression of CDKN2AIP induced germ cell apoptosis which contribute to age dependent infertility." (PMID 35989335, 2022).
liver cirrhosis (1 paper, 2024). "Recently conducted research identified significantly lower methylation rates in CDKN2AIP among the HCC and liver cirrhosis (LC) group compared to the LC only group 43." (PMID 39664575, 2024).
mesothelioma (1 paper, 2009). A usually malignant and aggressive neoplasm of the mesothelium which is often associated with exposure to asbestos.
testicular seminoma (1 paper, 2022). A malignant germ cell tumor arising from the testis. "CDKN2AIP induces testicular seminoma cell senescence by suppressing CARM1 expression and eIF4β phosphorylation." (PMID 35593475, 2022). "The results showed that CDKN2AIP is highly expressed in normal testis samples, and is significantly suppressed in testicular seminoma clinical samples and cell line model." (PMID 35593475, 2022). "In summary, through clinical samples combined within vitro tumor cell line and mouse xenograft model experiments, we demonstrated for the first time that CDKN2AIP induces testicular seminoma cell senescence and suppresses CARM1 expression and eIF4β phosphorylation." (PMID 35593475, 2022). "Therefore, in this study, we aimed to further investigate the role of CDKN2AIP in testicular seminoma pathogenesis and disease progression." (PMID 35593475, 2022). "The CDKN2AIP-CARM1 and CDKN2AIP-eIF4β interactions, which induce tumor cell senescence and apoptosis, may be the potential druggable molecular pathways in testicular seminoma tumor pathogenesis and progression." (PMID 35593475, 2022). "In addition, due to the nature of CDKN2AIP’s dual functions in both germ cell formation and testicular seminoma pathogenesis, it serves as a representative for a novel cluster of genes named as ‘Cancerous-Testis Gene Cluster’ which may include more candidates." (PMID 35593475, 2022).
cancer (8 papers, 2010 to 2025). A tumor composed of atypical neoplastic, often pleomorphic cells that invade other tissues. "Furthermore, the expression of CARF (collaborator of p14ARF)/CDKN2AIP mRNA that has been shown to regulate Wnt/β-catenin mediated EMT in cancer cells showed a significant decrease in Wi-ACAPE-treated cells." (PMID 35159054, 2022). "Interestingly, abnormally-high expression of CDKN2AIP unexpectedly exhibits promotive effects on cancer expansion, and CDKN2AIP promotes cell malignant transformation through transcriptional repression of p21." (PMID 35593475, 2022). "CDKN2AIP was reported to be pertinent to cell fate and has two-way effects on cancer cells." (PMID 34637672, 2021). "Furthermore, CDKN2AIP has been reported to be targeted by miRNAs, and play extensive regulatory roles in cancer, such as miR-451 and miR-335." (PMID 34637672, 2021). "Significantly lower expression of CDKN2AIP and higher level of CARM1 were observed in NTERA-2 and U2OS cell lines, which are all human cancer cells." (PMID 35593475, 2022). "However, the mechanism of CDKN2AIP in the regulation of angiogenesis in cancer remains unclear." (PMID 34637672, 2021). "On the other hand, CDKN2AIP overexpression was confirmed to enhance malignant properties in cancer cells, and could serve as the marker involved in EMT and invasion in cancer." (PMID 34637672, 2021). "The smallest region of overlap (region 4q35.1-4q35.2) encompasses the cancer associated genes TLR3, CDKN2AIP, ING2, CASP3 and SORBS2, none of which are thought to cause aberrant DNA methylation." (PMID 20444249, 2010). "Thus, it is not surprising that CDKN2AIP represents a potential therapeutic target for cancer treatments and is suggested to be an important factor in the ageing process." (PMID 35748965, 2022).
tumor (8 papers, 2013 to 2024). "Given the critical role of CDKN2AIP in cell proliferation progression 23, 24, we investigated the role and underlying mechanism of CDKN2AIP in the tumor inhibitory role of NR4A3 in HCC." (PMID 39664575, 2024). "Despite limited research on CDKN2AIP, particularly beyond its relevance in DNA damage response 24, 40, 41, existing reports suggest that CDKN2AIP functions either as a tumor suppressor or an oncogene depending on the specific tumor type." (PMID 39664575, 2024). "The protein levels of NR4A3 and CDKN2AIP in mouse tumor tissues were examined by Western blot analyses." (PMID 39664575, 2024). "The results indicated that NR4A3 upregulated the protein expression of CDKN2AIP and inhibited the G0/G1 phase pathway activity in xenograft tumor tissues derived from NR4A3 overexpressed cells." (PMID 39664575, 2024). "Our study provided evidence that CDKN2AIP exhibits cell senescence-inducing function by suppressing CARM1, which further expands the regulatory molecular network of CDKN2AIP on tumor cell senescence." (PMID 35593475, 2022). "Tumor expansion results demonstrated that CDKN2AIP overexpression significantly suppressed tumor growth, decreased tumor volume and weight." (PMID 35593475, 2022). "Subsequent qRT-PCR and western blot analysis demonstrated that the mRNA and protein level of CDKN2AIP was significantly lower in tumor tissues than in normal tissues." (PMID 35593475, 2022). "CDKN2AIP functions as tumor suppressor through two diverse routes: on one hand, CDKN2AIP induces cell senescence by interacting with CARM1, and on the other hand, CDKN2AIP also induces apoptosis by interacting with eIF4β and reduces eIF4β phosphorylation." (PMID 35593475, 2022). "It was found that the tumor cell senescence was significantly increased in CDKN2AIP-overexpressing NTERA-2 cell group, compared with that in the control cell group." (PMID 35593475, 2022). "Meanwhile, IHC study confirmed that the expression level of CDKN2AIP in xenograft tumor tissue was significantly up-regulated in the CDKN2AIP overexpression group." (PMID 35593475, 2022). "CDKN2A interacting protein (CDKN2AIP) has previously been identified as a tumor suppressor in multiple malignant diseases." (PMID 35593475, 2022). "Then, we detected CDKN2AIP expression in clinical tumor tissues and found that miR-127-5p was negatively correlated with CDKN2AIP." (PMID 34637672, 2021). "In conclusion, our findings provide initial evidence suggesting that NR4A3 suppresses HCC cell proliferation by regulating levels of CDKN2AIP expression, thereby playing a pivotal role as a tumor suppressor during HCC progression both in vitro and in vivo settings." (PMID 39664575, 2024). "CDKN2AIP exhibits anti-tumor activity by interacting with CARM1 and eIF4β." (PMID 35593475, 2022). "Moreover, in this study we also demonstrated for the first time that CDKN2AIP exhibited anti-apoptotic functions against tumor cell survival by suppressing the phosphorylation of eIF4β." (PMID 35593475, 2022). "Therefore, more detailed studies are required to fully unveil the regulator network of CDKN2AIP in tumor pathogenesis." (PMID 35593475, 2022). "Moreover, CDKN2AIP overexpression was also found to induce tumor invasion and metastasis through transcriptional activation of Wnt/β-Catenin and subsequent epithelial mesenchymal transition (EMT) enhancement." (PMID 35593475, 2022). "Moreover, CDKN2AIP plays a crucial role in genome preservation and tumor suppression." (PMID 39664575, 2024).
tumor (continued). "The CDKN2AIP-CARM1 and CDKN2AIP-eIF4β interaction-induced tumor cell senescence and apoptosis may be potential druggable molecular pathways in testicular seminoma tumor pathogenesis and progression, which will promote novel therapy development in future testicular seminoma-related research." (PMID 35593475, 2022). "Meanwhile, the diminishment of tumor growth induced by NR4A3 overexpression were significantly inhibited by CDKN2AIP knockdown in MHCC-LM3 cells, which confirming the role of CDKN2AIP in NR4A3-mediated inhibition of cell proliferation." (PMID 39664575, 2024). "CDKN2A interacting protein (CDKN2AIP), also known as collaborator of ARF (CARF), is a newly discovered marker involved in tumor pathogenesis." (PMID 35593475, 2022). "Secondly, to further explore the detailed mechanism of the effect of CDKN2AIP on testicular seminoma pathogenesis, we utilized IP-MS assay in NTERA-2 tumor cell line to detect CDKN2AIP-interacting proteins." (PMID 35593475, 2022). "For example, PTEN, RBL1, CDKN2AIP, RNASET2A, HINT1, and PARP12 are well-known tumor suppressors and were downregulated or absent in the CT26/SCID tumors." (PMID 38672200, 2024). "Firstly, NTERA-2 cells with or without transfection of CDKN2AIP overexpression plasmids were respectively inoculated into SCID mice, tumor growth was monitored and tumor tissue samples were subsequently collected to detect the CDKN2AIP protein expression level." (PMID 35593475, 2022).
CDKN2AIP also shares sentences with these, for which no sentence is quoted: autism (1 paper); breast carcinoma (1); hepatocellular carcinoma (1); kidney cancer (1); liver cancer (1); malignant melanoma (1).